GHRHR (growth hormone releasing hormone receptor)
Description:
Receptor for GRF, coupled to G proteins which activate adenylyl cyclase. Stimulates somatotroph cell growth, growth hormone gene transcription and growth hormone secretion.
Synonyms: GRFR; GHRFR; IGHD1B; IGHD4
Tractability: Small molecule: a structure with a bound ligand is known; it belongs to a druggable protein family. Antibody: its Gene Ontology location is reachable by antibodies, with high confidence; UniProt places it where antibodies can reach, with medium confidence; UniProt predicts a signal peptide or a membrane-spanning region. PROTAC: a small molecule that binds it is known. Other modalities: an approved drug acts on it.
Target class: Peptide receptor (family B GPCR); Family B G protein-coupled receptor; Glucagon-like receptor; Growth hormone-releasing hormone receptor; Membrane receptor
Gene: Protein-coding gene on chromosome 7 (30,938,669 to 30,993,254, forward strand). Ensembl gene ENSG00000106128.
Subcellular location: Cell membrane
Pathways (Reactome):
Signal Transduction: G alpha (s) signalling events; Glucagon-type ligand receptors
Gene Ontology:
Molecular function: growth factor binding; growth hormone-releasing hormone receptor activity; peptide hormone binding; protein binding; G protein-coupled peptide receptor activity; G protein-coupled receptor activity; transmembrane signaling receptor activity
Biological process: adenylate cyclase-activating G protein-coupled receptor signaling pathway; positive regulation of cell population proliferation; positive regulation of multicellular organism growth; response to estrogen; response to glucocorticoid; response to insulin; positive regulation of growth hormone secretion; positive regulation of insulin-like growth factor receptor signaling pathway; cAMP/PKA signal transduction; cell surface receptor signaling pathway; cellular response to glucose stimulus; G protein-coupled receptor signaling pathway; positive regulation of circadian sleep/wake cycle, non-REM sleep
Cellular component: cell surface; cytoplasm; membrane; nuclear inner membrane; nuclear matrix; nuclear outer membrane; plasma membrane; secretory granule; sarcolemma
Genetic constraint (gnomAD): Loss-of-function variants: 30 observed, 41.34 expected, observed/expected ratio (o/e) 0.73, 90% interval 0.54 to 0.98. The upper end of that interval is the gene's LOEUF score, 0.98, which puts it in group 4 of 6, group 1 being the genes least tolerant of losing a copy. Missense variants: 422 observed, 419.83 expected, observed/expected ratio (o/e) 1.01, 90% interval 0.93 to 1.09. Synonymous variants: 202 observed, 171.78 expected, observed/expected ratio (o/e) 1.18, 90% interval 1.05 to 1.32.
Homologues: Orthologues: chimpanzee GHRHR (99% identical), chimpanzee GHRHR (98% identical), macaque GHRHR (96% identical), dog GHRHR (87% identical), pig GHRHR (86% identical), guinea pig GHRHR (84% identical), rat Ghrhr (82% identical), mouse Ghrhr (82% identical), zebrafish ghrhrl (16% identical). Paralogues in human: VIPR1 (43% identical), ADCYAP1R1 (43% identical), SCTR (41% identical), VIPR2 (39% identical), PTH1R (35% identical), GLP1R (35% identical), GLP2R (33% identical), GCGR (32% identical), PTH2R (31% identical), GIPR (30% identical), CALCR (27% identical), CALCRL (25% identical), and 30 more.